CAV1 (caveolin 1)
Diseases named in the same sentence as CAV1 in open-access papers (continued):
Sharing a sentence is not in itself a finding about the gene and the disease.
ocular hypertension (7 papers, 2016 to 2025). Abnormally high intraocular pressure. "Using gain- and loss-of-function approaches, we found that Cav1 protects RGCs against acute ocular hypertension stress injury." (PMID 28878269, 2017). "We show that Cav-1-deficient (Cav-1−/−) mice display ocular hypertension explained by reduced pressure-dependent drainage of aqueous humor." (PMID 27841369, 2016). "Interestingly, we observed the opposite; significant ocular hypertension in Cav-1-deficient mice that was sustained at several ages." (PMID 27841369, 2016). "–45 To determine whether the observed ocular hypertension and dysfunctional pressure-dependent CO homeostasis resulted from loss of Cav1 expression and function specifically in the SC and/or distal vascular endothelium, we measured IOP and outflow facility in Cav1ΔEC mice." (PMID 32940661, 2020). "Regardless, there is likely to be another mechanism whereby ablation of endothelial Cav1 results in ocular hypertension." (PMID 32940661, 2020). "In genetic association studies, polymorphisms at the Cav1/2 gene loci have been reproducibly implicated in POAG and ocular hypertension." (PMID 32940661, 2020). "A 1 μl volume of 10 mM cavtratin, a peptide containing the Cav1 scaffolding domain, or the control peptide AP, was injected into the vitreous chamber 4 hr before the ocular hypertension treatment." (PMID 28878269, 2017). "To further verify the protective role of Cav1, we applied cavtratin to the Cav1 KO mice, and checked the apoptosis in the retina after the acute ocular hypertension treatment." (PMID 28878269, 2017). "In summary, this study demonstrates that Cav1 is a neuroprotective factor in the acute ocular hypertension injury animal model." (PMID 28878269, 2017). "To explore the role of Cav1 in ocular hypertension, we performed TUNEL staining on the retinae of both WT and Cav1 KO mice after the acute ocular hypertension treatment." (PMID 28878269, 2017). "Even though several GWAS have reproducibly implicated the association of Cav-1 polymorphisms with POAG and other ocular hypertension metrics, the limitations of GWAS should be considered in all future studies to enhance the statistical power enabling the actual and not misleading associations." (PMID 37962455, 2024). "Thus, increased resistance to CO in the TM/SC cannot explain ocular hypertension resulting from ablation of endothelial Cav1." (PMID 32940661, 2020). "To explore whether Cav1 was involved in the pathogenesis of acute ocular hypertension injury, we examined its expression in the retina of an animal model." (PMID 28878269, 2017). "The absence of Cav-1 leads to defective neurovascular coupling at the optic nerve head, ocular hypertension, and increased vessel density." (PMID 37962455, 2024). "This increase was not evident in Cav-1-/- mice in chronic model and was also not observed in either WT or Cav-1-/- mice in acute ocular hypertension model." (PMID 33995651, 2021). "It’s interesting that, similar to the insignificant difference of apoptosis between WT and Cav1 KO in the INL under the ocular hypertension condition, the rescue effect in the INL was not different as well." (PMID 28878269, 2017). "Under the acute ocular hypertension injury, three days after IOP recovery, the number of TUNEL+ cells in the Cav1 KO group was approximately 45.3% higher than that in the WT group (WT: 40.50 ± 6.273; Cav1 KO: 74.04 ± 7.775; n = 4 for both; p = 0.0153)." (PMID 28878269, 2017).
renal fibrosis (7 papers, 2021 to 2025). A final common manifestation of a wide variety of chronic kidney diseases characterized by glomerulosclerosis and tubulointerstitial fibrosis. "Evidence for the role of Cav-1/autophagy in urinary system diseases (e.g., nephrolithiasis, renal fibrosis) and hematopoietic system diseases remains limited and requires more exploration." (PMID 41030451, 2025). "Our group also found significant hypoxia in a rat model of advanced renal fibrosis; moreover, we found that caveolin-1 expression was upregulated and that endocytosis was active in both this model and hypoxic cultured renal tubular epithelial cells." (PMID 36185410, 2022). "Previously, we demonstrated that the antifibrotic protein follistatin (FST) is transcriptionally upregulated in cav-1 knockout MC and that its administration is protective against renal fibrosis." (PMID 33420269, 2021). "With increased research on Cav-1, it has been demonstrated that Cav-1 plays an important role in the process of renal fibrosis." (PMID 34955837, 2021). "In this study, we observed that the deletion of the Cav1 gene can ameliorate renal fibrosis." (PMID 39887553, 2025). "In the previous studies, genetic polymorphisms such as caveolin-1 and SHROOM3 promoted the formation of renal fibrosis and increased risks of allograft failure, reminding genetic factors are worth of further investigation in the exploration of renal graft fibrosis." (PMID 34950738, 2021). "Furthermore, the CAV1 rs4730751 SNP independently predicted transplanted renal fibrosis and allograft failure, and the late allograft biopsies showed the incidence of renal IF/TA was higher in the AA group (59% vs. 26%)." (PMID 34950738, 2021). "The upregulation of caveolin-1 expression affects the hyperglycosylation of CD147, leading to insufficient MMP-2 activation; in addition, the hypoxic conditions in renal fibrosis evoke intense endocytic activity, which drastically alters the structure of the cell membrane." (PMID 36185410, 2022).
tongue squamous cell carcinoma (7 papers, 2012 to 2021). A squamous cell carcinoma that arises from the tongue. "The aim of our study was to investigate the differential expression of CAV1 in cancer cells and in the TME of tongue SCC (TSCC) and to determine possible associations with clinical outcome." (PMID 25633184, 2015). "We investigated CAV1 in tongue squamous cell carcinoma (TSCC) and its association with clinical outcomes, and studied in vitro possible ways for CAV1 accumulation in the tumor microenvironment (TME)." (PMID 25633184, 2015). "Furthermore, we performed αSMA immunostaining since the peri-tumoral location of the CAV1-positive spindle cells recapitulated the arrangement of CAFs in the human tongue SCC case." (PMID 25633184, 2015).
amyotrophic lateral sclerosis (6 papers, 2020 to 2023). "Another study confirmed that swimming training prolonged the lifespan of amyotrophic lateral sclerosis (ALS) mice accompanied by changes in MAM components, such as lower mitochondrial cholesterol and enhanced caveolin-1 expression." (PMID 35805170, 2022). "For example, neuron-targeted Cav1 has been shown to improve synaptic plasticity in cultured hippocampal neurons, preserve memory and restore motor function induced by brain trauma in the ALS (Amyotrophic Lateral Sclerosis) mouse model." (PMID 33020520, 2020). "There is converging evidence that CAV1 and CAV2 (CAV1/2) genes have a role in amyotrophic lateral sclerosis (ALS)." (PMID 36937187, 2023).
Arrhythmia (6 papers, 2013 to 2025). Any cardiac rhythm other than the normal sinus rhythm. "SCN10A, SCN5A, and CAV1 have roles in cardiac conduction and arrhythmia." (PMID 39540287, 2024).
emphysema (6 papers, 2009 to 2025). "CS also inhibits PP2A responses, which contributes to COPD pathogenesis, further linking caveolin-1 signaling to cellular senescence and emphysema." (PMID 35744080, 2022). "Caveolin-1, the structural protein component of caveolae, has been shown to protect against emphysema through the regulation of cellular senescence." (PMID 35744080, 2022). "CDKN1A mediates cigarette smoke-induced inflammation; cigarette smoke increases expression of CAV-1 which is involved in senescence and pulmonary emphysema induction." (PMID 22829758, 2012). "We found that, in contrast to wildtype mice, the development of pulmonary emphysema was significantly inhibitedin caveolin-1 null mice." (PMID 20157570, 2009). "Another player in this complex scenario is likely represented by caveolin-1, the member of a protein family involved in the formation of cellular caveolae, that plays divergent roles in the development of IPF and emphysema, respectively." (PMID 22235752, 2012). "Recently, we reported that thedevelopment of cigarette smoking-induced pulmonary emphysema was inhibitedin caveolin-1 null mice, which do not express caveolin-1." (PMID 20157570, 2009).
endometrial cancer (6 papers, 2015 to 2023). Primary or metastatic malignant neoplasm involving the endometrium (mucous membrane that lines the endometrial cavity). "Upregulated levels of WTAP expression facilitate the growth and progression of endometrial cancer via the caveolin-1 (CAV-1)/nuclear factor-κB (NF-κB) axis and are associated with worse survival outcomes." (PMID 35143566, 2022). "Our study shows that elevated CAV1, observed in patients with endometrial cancer, is linked to enhanced malignancy of endometrial cancer cells, as evidenced by increased migration, invasion and anchorage-independent growth." (PMID 26054531, 2015). "The decrease in the level of these miRNAs with the grade of cancer with a simultaneous increase in CAV1 level may indicate that the progression of endometrial cancer is accompanied by a loss of the protective effect of these miRNAs." (PMID 37233761, 2023). "Endometrial cancer is one of the most common malignancies of the female genital tract; however, little is known about the role of CAV1 in this disease." (PMID 26054531, 2015). "Besides, WTAP acts as a tumor suppressor gene by methylating 3'-UTR of CAV-1 and then activating NF-κB signaling pathway in endometrial cancer." (PMID 37325054, 2023). "However, in a microarray study of type I endometrial cancer biopsies, a decrease in CAV1 mRNA was reported when compared with control samples." (PMID 26054531, 2015). "Also, in Ishikawa and Hec-1A endometrial cancer cells CAV1 expression was readily detectable." (PMID 26054531, 2015). "Thus, whether CAV1 is expressed and how the protein may contribute to the development of endometrial cancer remains an open question." (PMID 26054531, 2015). "Then using two endometrial cancer cell lines (ECC: Ishikawa and Hec-1A) we evaluated mRNA and protein levels of CAV1 by real time qPCR and Western blot analysis, respectively." (PMID 26054531, 2015). "In cultured human endometrial cancer (CHEC) cells, increased CAV1 expression is observed during epithelial-mesenchymal transition (EMT)." (PMID 26054531, 2015). "Mechanistic studies showed that WTAP increased the m6A modification of caveolin 1 (CAV-1) mRNA 3′-UTR and downregulated CAV-1 expression, thereby activating the NF-κB signaling pathway in endometrial cancer to maintain the malignant characteristics of tumor cells." (PMID 36139062, 2022). "However, to our knowledge, no reports are available indicating how 4β − TPA affects CAV1 expression and whether this relates to tumor promotion in endometrial cancer cells (ECC)." (PMID 26054531, 2015).
gastric tumors (6 papers, 2017 to 2023). "Bidirectional alteration of Cav-1 is linked to its opposite effects on gastric tumor cell growth, which stem from the reciprocal control on the RAF-ERK negative feedback loop." (PMID 29141593, 2017). "The gastric PDX model was established by implantation of HER2-positive and CAV1-positive gastric tumor tissue from Patient 1 in immunodeficient NOD-SCID gamma (NSG) mice." (PMID 30510281, 2018). "To address the biological significance of bidirectional alteration of Cav-1 in gastric tumor progression, we examined its effects on tumor cell growth." (PMID 29141593, 2017). "Our previous study showed that high Cav-1 expression enhances the metastatic potential of gastric tumor cells by increasing the adhesion ability of the cells to endothelium through the regulation of cell surface VCAM." (PMID 29141593, 2017). "Further studies will be required to address whether Cav-1 gene expression in CAFs also shows a bidirectional alteration due to promoter hypo- and hyper-methylation during gastric tumor progression." (PMID 29141593, 2017). "On the other hand, in gastric tumors with patchy HER2 membrane localization, the pharmacological depletion of caveolin 1 successfully forces HER2 to the cell surface for improved trastuzumab and pertuzumab efficacy." (PMID 33348564, 2020). "We validated that in EGF-treated gastric tumor cells, RAF is inhibited by ERK feedback phosphorylation and this feedback loop is differentially regulated by Cav-1 in these two cell types." (PMID 29141593, 2017).
generalized lipodystrophy (6 papers, 2013 to 2024). Almost complete absence of subcutaneous and/or visceral adipose tissue. "The main known candidate genes associated with congenital generalized lipodystrophy, i.e. BSCL1/AGPAT2, BSCL2/seipin, BSCL3/caveolin-1 and BSCL4/PRTF were analyzed." (PMID 23919306, 2013). "In the case of genes causing generalized lipodystrophy, this may reflect the fact that while disruption of BSCL2 or AGPAT2 leads principally to a lack of adipose tissue, PTRF and CAV1 mutations cause a more complex phenotype in affected patients." (PMID 30940487, 2019).
Hyperinsulinemia (6 papers, 2014 to 2024). An increased concentration of insulin in the blood. "Additionally, cav-1-deficient mice had higher plasma insulin levels and postprandial hyperinsulinemia under fasting or high-fat diet conditions." (PMID 31728004, 2019). "Relative to littermate controls, CAV1 knockout (KO) mice suffer from hyperinsulinemia under fasting conditions and when fed with high-fat diet (HFD)." (PMID 32082483, 2020). "The Cav-1 knockout mice fed a high-fat diet to induce T2D developed postprandial hyperinsulinemia." (PMID 35250626, 2022).
meningioma (6 papers, 2015 to 2024). A generally slow growing tumor attached to the dura mater. "In the present study, serum Cav1 was increased significantly after RT when compared to before RT in GB patients and was higher than its levels in meningioma patients." (PMID 36121548, 2022). "In meningioma subgroup, the mean ± SD of serum Cav-1 was 8.11 ± 1.74 pre-RT that was increased to 8.56 ± 1.56 post-RT." (PMID 36121548, 2022). "Importantly, CAV1 was shown to correlate with increased angiogenesis in meningioma." (PMID 29662628, 2018).
non-alcoholic fatty liver disease (6 papers, 2020 to 2025). "CAV1 was found to attenuate the Akt/mTOR pathway and hence alleviate lipid accumulation in non-alcoholic fatty liver disease." (PMID 39444451, 2024). "We aimed to analyze the consequences of hepatocyte-specific Cav1 knockout under healthy conditions and upon non-alcoholic fatty liver disease (NAFLD) development." (PMID 32029710, 2020). "Clinical studies indicate elevated serum Cav-1 levels in non-alcoholic fatty liver disease (NAFLD) patients, accompanied by cell-type-specific expression patterns, hepatocyte Cav-1 downregulation contrasts with macrophage-specific upregulation in vivo." (PMID 40430042, 2025).
pancreatic adenocarcinoma (6 papers, 2002 to 2020). "Recent immunohistochemical studies have implicated increased cav-1 expression as a poor prognostic factor for pancreatic adenocarcinoma (PC)." (PMID 15969750, 2005). "In the current study we investigated the role of caveolin-1 (cav-1) in pancreatic adenocarcinoma (PC) cell migration and invasion; initial steps in metastasis." (PMID 15969750, 2005). "In this study, we have investigated the relationship between caveolin-1 expression and the clinicopathologic variables and clinical outcome in 79 patients with pancreatic adenocarcinoma undergoing surgical resection." (PMID 12402154, 2002). "Ten pancreatic adenocarcinoma (PC) cell lines were obtained from ATCC and compared with immortalized human pancreatic ductal epithelial (HPDE) cells for caveolin-1 (cav-1) expression." (PMID 15969750, 2005). "Also, mechanistic insight as to how CAV1 distribution may be modulated came by showing that CAV1 phosphorylation on specific residues, such as serine 80, targeted CAV1 to the secretory pathway rather than to caveolae in AR42J pancreatic adenocarcinoma cells." (PMID 32458269, 2020).
papillary carcinoma (6 papers, 2002 to 2025). A malignant epithelial neoplasm characterized by a papillary growth pattern. "CAV1 is highly expressed in thyroid anaplastic carcinomas, and in papillary carcinomas it is considered as an indicator of tumor progression." (PMID 29487711, 2018). "Although there existed no changes in the protein levels of Cav-1 between control cells or Galectin-3 knockdown cells, a co-localization of Galectin-3 (red) and Cav-1 (green) was found in papillary thyroid carcinoma tissue." (PMID 29254179, 2017). "In summary, this study indicates that, in papillary carcinomas, caveolin-1 plays a role in the early phase and its decreased expression is linked to aggressive characteristics including dedifferentiation." (PMID 11953823, 2002). "As there is no striking difference between the prognosis of patients with follicular carcinoma and papillary carcinoma, regulation of some other type than caveolin-1 must operate for signal transduction in follicular carcinomas." (PMID 11953823, 2002). "In anaplastic (undifferentiated) carcinomas, only four cases (12.5%) were positive for caveolin-1, which was significantly lower than in type B papillary carcinomas." (PMID 11953823, 2002). "In papillary carcinomas, caveolin-1 was more frequently positive in microcancers than those of larger size, indicating that caveolin-1 expression is an early event in papillary carcinoma." (PMID 11953823, 2002). "In papillary carcinoma, caveolin-1 expression was observed in high incidence, and especially in microcancer (less than 1.0 cm in diameter), caveolin-1 was positive in all cases except one." (PMID 11953823, 2002). "Of the 85 papillary carcinomas, 57 cases (67.1%) were judged as positive for caveolin-1." (PMID 11953823, 2002). "In this study, we have demonstrated that caveolin-1 was frequently positive in papillary carcinoma, but not in tumours of the follicular type." (PMID 11953823, 2002). "However, in contrast to the papillary carcinomas, caveolin-1 immunoreactivity was not seen in the tumour cells of these tissues, and all these cases were classified as negative, regardless of histological type." (PMID 11953823, 2002).
primary open-angle glaucoma (6 papers, 2012 to 2022). "Mutations in the caveolin-1 (Cav-1) gene have been found to be associated with an increase genetic risk of open-angle glaucoma." (PMID 34819834, 2021).
prostate adenocarcinoma (6 papers, 2008 to 2024). "TCGA data on prostate adenocarcinomas was stratified into the highest or lowest CAV1 expression quartiles to evaluate the association between CAV1 mRNA expression and mRNA expression of genes involved in sphingolipid metabolism amongst the most differential populations." (PMID 32855410, 2020). "Therefore, formalin fixed paraffin-embedded tissue slides of human prostate adenocarcinomas with distinct Gleason Scores were immunostained for Cav1, phosphoCav1, Src and Tagln." (PMID 28112237, 2017). "Therefore, formalin-fixed paraffin-embedded tissue slides of human prostate adenocarcinomas with distinct Gleason scores were immunostained for Cav1." (PMID 25985209, 2015). "Moreover, re-expression of CAV1 at latter stages of tumor development has been described in human and mouse prostate adenocarcinomas, a scenario that could resemble chemotherapy resistance." (PMID 18694510, 2008). "Increased levels of phosphorylated CAV1 and SRC were even found within malignant epithelial cells of advanced human prostate adenocarcinomas." (PMID 35155239, 2022).